RELN (reelin)
Diseases named in the same sentence as RELN in open-access papers (continued):
Sharing a sentence is not in itself a finding about the gene and the disease.
Lissencephaly (continued). "Among these, lissencephaly 2 (LIS2) and autosomal-dominant lateral temporal epilepsy (ADLTE) are of relevance to the present discussion as they have a clear genetic link with RELN." (PMID 31805691, 2019). "Mutations of many genes are involved in neuronal migration disorders, such as LIS1 and DCX in classical lissencephaly spectrum, TUBA1A in microlissencephaly with agenesis of the corpus callosum, and RELN and VLDLR in lissencephaly with cerebellar hypoplasia." (PMID 26052266, 2015). "Histological examinations in TUBA1A mutated brains revealed structural abnormalities of the cortex, a fractured pyramidal layer of the hippocampus, and defects attributed to impairment of neuronal migration mechanisms, similar to the mouse models of lissencephaly (LIS1, DCX, RELN)." (PMID 31269740, 2019).
Cognitive impairment (41 papers, 2013 to 2025). Abnormal cognition is characterized by deficits in thinking, reasoning, or remembering. "Recently, a rare gain‐of‐function variant in RELN was identified in a patient with an autosomal dominant AD‐causing mutation, and it was associated with resilience against cognitive impairment." (PMID 41384508, 2025). "We characterized a male heterozygous for the RELN-COLBOS variant who was resilient to the cognitive impairment associated with the PSEN1-E280A mutation." (PMID 37188781, 2023). "In one PS1 case, the RELN variant H3447R (COLBOS) was associated with a delayed onset of cognitive impairment of over 20 years." (PMID 37891846, 2023). "Reelin signalling in multiple brain regions is involved in neuronal migration, synaptic plasticity and long-term potentiation, and has been implicated in cognitive deficits." (PMID 36979424, 2023). "Overall, the data presented suggest that the presumably protective RELN variant increases signaling and slows tauopathy, thereby delaying cognitive impairment in the described cases." (PMID 37891846, 2023). "RELN expression decreases early in AD prior to the deposition of amyloid pathology, and its loss is associated with cognitive deficits, several neuropsychiatric disorders, and loss of synapse maintenance." (PMID 33964983, 2021). "A number of molecular, anatomical (dendritic spine density), behavioral, and cognitive deficits associated with reduced RELN expression (mRNA and protein) are observed in subjects with SZ and BP disorder." (PMID 27092053, 2016). "The aim of this study was to demonstrate the effects of this novel HFE on anxiety, cognitive impairment, hippocampal dysfunction, and regulation of reelin methylation in the hippocampus of PTSD mice." (PMID 39339187, 2024). "Further, developmental disturbances in gene/protein expression and DNA methylation of downstream signalling components occurred subsequent to MIA-induced Reelin dysregulation and prior to cognitive deficits." (PMID 36979424, 2023). "In this model, microinjections of recombinant Reelin protein into the hippocampus rescued the cognitive impairments while increasing the synaptic protein recruitment." (PMID 37891846, 2023). "A decline in the levels of Reelin in the lateral entorhinal cortex of aged rats with cognitive impairment has also been observed." (PMID 37891846, 2023). "Despite these limitations, our findings, showing a relationship between MIA-induced dysregulation of the Reelin signalling pathway and the emergence of cognitive deficits, are supported by the literature." (PMID 36979424, 2023). "In particular, given our evidence for an adult cognitive deficit in MIA-affected offspring we were interested in the later developmental Reelin signalling pathway, which contributes to LTP through NMDA receptor modulation." (PMID 36979424, 2023). "Consistently, an increased Reelin protein level in AD mutant mice crossed with Reelin-overexpressing mice delays amyloid deposits, reduces synaptic loss, improves LTP and rescues memory-associated cognitive impairment." (PMID 32604886, 2020). "It was previously reported that RELN delays amyloid-β fibril formation and rescues cognitive deficits in an AD model." (PMID 30704480, 2019). "Reelin expression levels decrease with age and reduced Reelin expression contributes to cognitive deficits during normal aging." (PMID 30304853, 2018). "Reduced levels of RELN expression in the adult brain induce cognitive impairment and dendritic spine density deficits." (PMID 27092053, 2016). "We have previously reported an age-related reduction in Reelin levels and its accumulation in neuritic varicosities along the olfactory-limbic tracts, which correlated with cognitive impairments in aged mice." (PMID 24252415, 2013).
Cognitive impairment (continued). "Several human studies describe altered Reelin levels in AD: notably, the 180 kDa N-terminal Reelin fragment is significantly elevated in the cerebrospinal fluid (CSF) of AD patients compared to those with mild cognitive impairment (MCI) or healthy controls." (PMID 40806482, 2025). "Interestingly, genetic deletion of Reelin resulted in mice that exhibited neuropsychiatric disorders, cognitive impairment, and social-seeking behavior deficits." (PMID 39339187, 2024). "Therefore, further investigation into the contribution of Reelin signaling during aging and in disease pathogenesis would certainly advance our understanding of related cognitive impairment and lead to new brain-specific therapeutic targets." (PMID 37891846, 2023). "Suppression of RELN expression may contribute to cognitive deficits by limiting dendritic proliferation, affecting neurogenesis, and leading to improper neuronal circuits." (PMID 38137152, 2023). "This phenomenon is greatly enhanced both in AD mouse model and human LOAD cases, where Reelin deposits are co-localized with Aβ plaques, fibrillary tangles and correlate with cognitive deficits showing a distinct spatial and temporal function of Reelin in AD pathogenesis." (PMID 36213737, 2022). "In addition, we measured Reelin protein levels in CSF samples of patients with mild cognitive impairment (MCI), dementia, or sCJD diagnosis and a group of neurologically healthy cases." (PMID 32438605, 2020). "In addition, we analyzed through Western Blotting the Reelin protein levels in CSF samples obtained from patients with mild cognitive impairment (MCI), dementia, and sCJD compared with control cases." (PMID 32438605, 2020). "A previous study reported similar effects of Reelin, with intraventricular injections of Reelin rescuing synaptic dysfunction and hippocampus-dependent cognitive impairments in a mouse model of Angelman syndrome, a genetic disorder which impairs nervous system development." (PMID 32982694, 2020). "A reduction of reelin expression during aging may contribute to cognitive impairment; however, appropriate reelin-mediated signaling may delay the shift to mainly pathological aging." (PMID 29176942, 2017). "In conclusion, we demonstrated that HFE could help ameliorate anxiety-like behavior and cognitive deficit by restoration of hippocampal dysfunction, including plasticity and cellular and epigenetic changes, via regulation of the Reelin pathway and DNA methylation." (PMID 39339187, 2024). "Therefore, it should not come as a surprise that lower levels of Reelin are associated with cognitive impairments during aging." (PMID 37891846, 2023). "Indeed, there is increasing evidence of a role of Reelin in the adult brain on in learning and memory processes and that the disruption of Reelin signaling during aging and neurodegenerative diseases could contribute to cognitive impairments." (PMID 37891846, 2023). "Overall, the findings support a degree of sex-specific dysregulation of Reelin signalling in response to MIA, which appears to converge in similar cognitive deficits." (PMID 36979424, 2023). "We identified and positively validated five novel proteins (NCAM2, NPTXR, NRXN2, RELN, and CNTN2) as promising biomarkers for cognitive impairment following aSAH." (PMID 35602555, 2022). "The decreased level of Reelin impairs the activation of the Fyn-NMDAR2B-CREB signaling pathway, which leads to the cognitive impairment of ApoE4-TR mice." (PMID 27406263, 2016). "In addition, the suppression or reduction of Reelin expression or of its downstream pathway in animal models exhibit features of SCZ, such as cognitive impairments, psychosis vulnerability, and learning deficits." (PMID 37891846, 2023).
Cognitive impairment (continued). "We propose such changes contribute to the emergence of the observed PFC-mediated cognitive deficits we have identified in this model, and therefore provide preliminary evidence of a mechanistic relationship between MIA and developmentally disturbed Reelin signalling." (PMID 36979424, 2023). "Interestingly, an adolescent high-fat diet has been shown to selectively reduce Reelin-positive cells without affecting the downstream DAB1 in the mPFC, resulting in deficient NMDA-dependent LTD and pronounced cognitive deficits." (PMID 36979424, 2023). "As Reelin and its downstream markers play a critical modulatory role in the function of NMDA receptors (and subsequently LTP), we hypothesised that we would observe developmental dysregulation of the Reelin pathway, preceding the onset of cognitive deficits." (PMID 36979424, 2023). "Moreover, immunohistochemical investigations involving human brains revealed significantly decreased levels of Reelin in patients with mild cognitive impairments (MCI) and AD compared to non-demented subjects." (PMID 24252415, 2013). "Hence, following our previous work, which validated a PFC-mediated cognitive deficit in adult female rats exposed to MIA, as well as sex-independent deficits in recognition memory, our aim here was to evaluate the possible role of the Reelin pathway in contributing to these cognitive deficits." (PMID 36979424, 2023).
epilepsy (38 papers, 2010 to 2025). A brain disorder characterized by episodes of abnormally increased neuronal discharge resulting in transient episodes of sensory or motor neurological dysfunction, or psychic dysfunction. "Mutations of the reelin RELN gene are associated with an autosomal familial form of epilepsy; however, other variations were found in patients with sporadic MTLE without any family history." (PMID 38927072, 2024). "Nevertheless, based on the similarities between the phenotype of the reeler mouse and the pathological findings in resections of TLE patients, it seems plausible that impaired reelin signaling results in increased susceptibility to develop epilepsy." (PMID 35733853, 2022). "The protein reelin has been shown to be important for proper lamination of dentate granule cell layer (GCL) while changes in reelin expression have been implicated in epilepsy and neuropsychiatric disorders." (PMID 36092698, 2022). "Dysregulation of Reelin signaling has been associated with several brain disorders such as autism, schizophrenia, bipolar disorder, depression, Alzheimer’s disease and epilepsy." (PMID 34483838, 2021). "In particular, patients P20 and P25, who presented different epilepsy types, were found to harbor the same inherited missense variant in RELN (c.3712A > C, p.Asn1238His), initially rendering the results inconclusive." (PMID 33391346, 2020). "A heterozygous RELN variant (NM_005045: p.P672L) was present in a patient (P10) with epilepsy and multiple minor anomalies." (PMID 31134136, 2019). "Recent studies in human MTLE specimens and in animal epilepsy models have shown that a decreased expression and functional inactivation of the extracellular matrix protein Reelin correlates with GCD formation, but causal evidence is still lacking." (PMID 27516734, 2016). "It is unknown whether the proband's mother's history of glioma and epilepsy was caused by a mutation in RELN; more research is needed to determine whether glioma and epilepsy share a common pathway." (PMID 40217319, 2024). "In this context, the extracellular matrix protein Reelin—known for its role in neuronal positioning and synaptic plasticity—has also been implicated in structural remodeling during disease states, such as epilepsy, and may be influenced by neuroinflammatory processes triggered by gut dysbiosis." (PMID 40880682, 2025). "Moreover, genetic variants of reelin are associated with epilepsy and TLE development." (PMID 38927072, 2024). "Tubulin genes play a key role in several pathways of cortical development such as other genes encoding microtubule-related proteins (i.e., Lissencephaly 1, Doublecortin, Filamin A or Reelin genes) and when mutated, may cause specific brain malformations strictly associated with epilepsy." (PMID 31269740, 2019). "In consideration of this previous study indicating Reelin as closely associated with cell death in a chronic model of epilepsy, the present data now implicate that Reelin also may play a critical role in the early stages of epilepsy, as a result of Golgi complex fragmentation." (PMID 25790952, 2016). "Loss of reelin signaling may contribute to these morphological changes in patients with epilepsy." (PMID 26941603, 2016). "A common mechanism was suggested to underlie both RELN-dependent epilepsy and ASD, and is correlated with RELN haploinsufficiency, reducing protein levels to 50%." (PMID 38980724, 2024). "In line with neuronal migration defects related to reelin deficiency, decreased reelin expression was observed in tissue dissected from patients with TLE, and in the KA animal model of epilepsy." (PMID 36092698, 2022).
epilepsy (continued). "Reelin is also related to abnormal granule cell migration and dispersion in epilepsy patients, after seizure induction in animal models, and a reelin knockout mouse model had developmental defects." (PMID 35333953, 2022). "For instance, there is evidence from rodent epilepsy models, that the formation of GCD can be triggered by the loss of reelin-producing cells." (PMID 35733853, 2022). "The loss of the extracellular matrix protein Reelin, an important positional cue for neurons, correlates with GCD formation in MTLE patients and in rodent epilepsy models." (PMID 34483838, 2021). "Additional in vivo experiments are warranted to further elucidate the molecular mechanisms accompanying this Reelin-Golgi complex fragmentation in epilepsy models." (PMID 25790952, 2016). "In the present study, protein expression and glycosylation levels of 180-kDa Reelin fragments were comparable between control (healthy neurons) and PRNCs treated with 5 μM KA for 3 days (albeit early stage epilepsy)." (PMID 25790952, 2016). "A recent study reported that KA administration into the rat brain, resembling a chronic model of epilepsy in vivo, altered the proteolytic processing of Reelin." (PMID 25790952, 2016). "In humans, recessive RELN variants in the homozygous or compound heterozygous state are associated with different patterns of lissencephaly (LIS) with cerebellar hypoplasia (LCH), a severely disabling developmental disorder, often linked with epilepsy." (PMID 38980724, 2024). "Indeed, Reelin signaling dysfunction has been documented in several neurodevelopmental and neurodegenerative disorders including AD, PD, HD, and epilepsy." (PMID 31134199, 2019). "Golgi complex fragmentation and Reelin dysfunction may be considered as disease biomarkers, as well as therapeutic targets for epilepsy." (PMID 25790952, 2016). "The present results demonstrated that a dysfunctional Golgi-Reelin interaction may contribute to the disease pathophysiology of epilepsy." (PMID 25790952, 2016). "Reelin may also play a role in seizure control: epilepsy models have altered Reelin processing, which may be MMP-dependent." (PMID 27065802, 2016). "Moreover, GCD formation has been shown to be accompanied by a loss of Reelin-producing neurons in the hippocampus of MTLE patients and in rodent epilepsy models." (PMID 27516734, 2016). "DNA methylation in promoter may decrease gene expression, for example, increased methylation of reelin promoter resulted in the decrease of reelin expression in epilepsy model." (PMID 27903967, 2016). "Restoring and reinforcing the ER-lysosome-Golgi network and its interaction with Reelin could be exploited as novel therapeutic regimens for attenuating epilepsy and relevant neurodegenerative diseases." (PMID 25790952, 2016). "The question of whether reelin deficiency, in patients without mutations in the reelin gene, is a cause or consequence of epilepsy cannot be conclusively answered in studies on patient tissue samples." (PMID 35733853, 2022). "Accordingly, this KA-induced epilepsy likely contributed to the initiation of Golgi complex fragmentation and the disruption of Reelin protein processing, subsequently resulting in dysfunctions such as decreased secreted Reelin, as well as impaired glycosylation." (PMID 25790952, 2016). "Here, we focus on reelin (RELN) and doublecortin (DCX), whose functions with respect to neural migration and epilepsy are more elucidated." (PMID 40529445, 2025). "Moreover, in a study performed on human hippocampal sections from MTLE patients, the extent of GCD was found to be inversely correlated with the number of reelin-expressing CR cells, suggesting a link between reelin secretion and GCD in epilepsy patients." (PMID 35733853, 2022). "The stratification of ASD cases according to plasma reelin levels was independent of age or any other comorbid conditions such as epilepsy, despite some previous reports having found a correlation between this disorder and reelin." (PMID 32292362, 2020).
epilepsy (continued). "Moreover, the genes RELN and SIM1, regulated by PLZF overexpression, are involved in epilepsy and mental retardation, respectively." (PMID 23469216, 2013). "GCD has also been studied in animal models of epilepsy, where it was observed upon kainic acid (KA) intrahippocampal injections, with morphological similarity to granule cell malpositioning in the reeler mutant mouse lacking reelin expression." (PMID 36092698, 2022).